RNU7-63P (RNA, U7 small nuclear 63 pseudogene)
Synonyms: U7.63
Gene: Small nuclear RNA gene on chromosome 16 (8,705,456 to 8,705,517, reverse strand). Ensembl gene ENSG00000238417.
Homologues: Orthologues: macaque U7 (60% identical). Paralogues in human: RNU7-11P (85% identical), RNU7-2P (85% identical), RNU7-69P (85% identical), RNU7-1 (84% identical), RNU7-13P (84% identical), RNU7-52P (84% identical), RNU7-60P (84% identical), RNU7-6P (84% identical), RNU7-12P (82% identical), RNU7-25P (82% identical), RNU7-3P (82% identical), RNU7-41P (82% identical), and 142 more.